TLR3 (toll like receptor 3)
Diseases named in the same sentence as TLR3 in open-access papers (continued):
Sharing a sentence is not in itself a finding about the gene and the disease.
cancer (continued). "In addition, TL-532 activity is strictly dependent on TLR3, induces immunogenic caspase-mediated apoptosis of cancer cells and shows no toxicity towards primary normal cells." (PMID 37275475, 2023). "However, in our data, although the results were not significant, TLR3 did show a cancer-promoting effect." (PMID 35664309, 2022). "Interestingly, TLR3 is localized in lysosomes and might provide a way to execute LMP in cancer cells that are defective in Caspase-8 or perhaps independent of Caspase-8." (PMID 34822366, 2021). "This list will certainly increase in the future for signaling via TLR3, TLR7/8, and TLR9, promote Th1 responses, and various synthetic TLR ligands have been created, several of which have been shown to have antitumor effects in clinical trials in different types of cancer." (PMID 34572013, 2021). "Moreover, the interaction of TLR3 with dsRNA triggers a cascade to activate a wide range of downstream axes, such as p38, JNK and IFN regulatory factors, which in turn regulate apoptosis in cancer cells." (PMID 33336901, 2021). "In addition, whether RIPK1 and its interplay with TLR3 could play a role in CCA and regulate cancer cell invasion have also remained largely unknown." (PMID 33036630, 2020). "The results showed that TLR3, TRIF, RIG-I, MDA5, LGP2, and MAVS, which were reported to be expressed in the A549 cell line, were expressed in all these cells lines at both the mRNA and protein levels, indicating that the TLR–TRIF and RLR–MAVS pathways are constitutively intact in all cancer cells." (PMID 33490069, 2020). "Indeed, the TLR3/dsRNA inhibitor complex, a competitive and high affinity inhibitor of dsRNA binding to TLR345, blocked the capacity of J1.1 cell exosomes to induce expression of IFIT1 and IFNB1 in HSC3 cancer cells (J1.1+inh)." (PMID 30389917, 2018). "Furthermore, TLR3 antibody-neutralization and TLR3 siRNA knockdown reversed the polyI:C-suppression of survival and metastasis of A549 and NCI-H292, suggesting that polyI:C specifically acts on TLR3 protein to exert anti-cancer functions." (PMID 28427199, 2017). "However, previous data have stated that IRF3-dependent apoptotic pathway in both virus infected and cancer cells is triggered only by the activation of dsRNA-sensing cytoplasmic receptors and not by endosomal receptor TLR3." (PMID 25444175, 2015). "Interestingly, selected TLRs were downregulated in 'both' cancers, especially TLR2 and TLR3." (PMID 17280610, 2007). "However, the mechanisms linking CRNDE and TLR3 in malignant tumors have not been elucidated." (PMID 38169579, 2024). "TLR1 and TLR3 (Id:242667_at) exhibited reduced expression, and TLR4 (Id1552798_a_at) exhibited increased expression in individuals with cancer, independent of HPV (p < 0.05)." (PMID 39208235, 2024). "For instance, by activating Toll-like receptor 3 (TLR3), anthracyclines stimulate production of type I IFNs by cancer cells, and tumors lacking TLR3 or IFN-α receptor fail to respond to anthracycline chemotherapy." (PMID 33436557, 2021). "Because of the TLR3-, TLR7-, and TLR9-mediated CD8+ T-cell response in TH1 mode, agonists specific to these TLRs are used for cancer nonvaccines." (PMID 31480568, 2019). "Therefore, our data suggest that pMSCs could be used to treat cancers by enhancing the anti-cancer activity of NK cells in vitro through different mechanisms that would involve IL-12, IL-18, and IFN-ɣ receptors, as well as TLR3 and IL1ra as we previously suggested for DPMSCs." (PMID 30728068, 2019). "Our results suggest that increased TLR3 expression and TLR3-mediated CXCL10 induction is an attribute of cancer IECs rather than healthy IECs." (PMID 28717003, 2017).
cancer (continued). "Given this, we hypothesised that TLR1, TLR2, TLR3, TLR7, TLR8, and TLR9 would be involved in a negative regulatory mechanism mediated by TLR8-AS1 that contributes to the maintenance of cancer stem cell features." (PMID 35801728, 2022). "Therefore, RIG-I, rather than TLR3 or MDA5, is required for sensing cytosolic nucleic acids in human cancer cells." (PMID 33490069, 2020). "However, studies that analyzed cytobrush samples of CIN detected no TLR3 differences even in patients with persistent infection, and others showed increased expression of this TLR in carcinoma and in dysplastic epithelium." (PMID 33013878, 2020). "Therefore, the identification of nuclear TLR3 provides new insight into non-classical functions of innate immune sensors in cancer, and JAK1/TLR3/PRMT5/c-Myc axis may sever as a potential prognostic indicator and therapeutic target to overcome chemoresistance." (PMID 40675966, 2025). "Furthermore, dsRNA accumulated within the nuclei of cancer cells in a dosage-dependent way post the treatment of GEM, and the dsRNA/TLR3 competitive binding inhibitor did not affect the nuclear translocation of TLR3." (PMID 40675966, 2025).
bacterial infection (40 papers, 2010 to 2025). "The results of this study show that TLR3 may play a risk role in AECOPD patients, possibly due to viral and bacterial infection induced TLR3 activation." (PMID 29264743, 2018). "Secondary bacterial infection was induced after the lung TLR3-mediated inflammation of RSV infection." (PMID 39766307, 2024). "Studies have found that TLR3 and TLR22 are also involved in defending pathogenic microorganisms, with their expression levels being up-regulated after bacterial infection." (PMID 39335239, 2024). "For A. hydrophila challenge, the transcription of hybrid yellow catfish TLR3 was increased to a significantly higher degree in the spleen after the bacterial infection for 24 and 48h." (PMID 36670828, 2023). "For example, TLR3 in Japanese sea perch was found highly expressed in the immune tissues and upregulated significantly after bacterial infection." (PMID 36670828, 2023). "TLRs located on the endosomal membrane (TLR3, 7, 8, and 9) are crucial for protecting the host against various viral and bacterial infections." (PMID 32660060, 2020). "We propose that the TLR3-dependent induction of IL-12p70 is of special importance in coinfections with IAV, as severe bacterial diseases, and in particular those caused by pneumococci, often occur 1 to 2 weeks after the onset of IAV infections." (PMID 26956584, 2016). "To address this question, we pretreated PBMCs with increasing concentrations of EPs 7630 (0.1–3 μg/ml) for 24 h followed by stimulation with TLR3 or TLR4 ligands (mimicking viral or bacterial infection, respectively) for another 24 h." (PMID 26406906, 2015). "To conclude; a combined TLR3- and TLR4-stimulation, representing a concomitant viral and bacterial infection, causes an AHR that is further exaggerated during an ongoing allergic inflammation." (PMID 26494305, 2015). "To summarize, a combined TLR3- and TLR4-stimulation, representing a concomitant viral and bacterial infection, caused an AHR that was further exaggerated during an on-going allergic inflammation." (PMID 26494305, 2015). "Work remains to be done to clearly delineate the precise role of TLR3 in viral and bacterial infections and to appraise the benefit afforded by TLR3 agonistic or antagonistic strategies for infectious diseases, especially septic shock." (PMID 24302927, 2013). "Furthermore, TLR3 has been found to participate in the immune process against bacterial infection in hybrid yellow catfish." (PMID 36670828, 2023). "Recent results with extracellular bacterial infections demonstrate that phagocytosed microbial RNA can be sensed by a combination of transmembrane PRRs such as TLR3 and cytosolic PRRs such as NLRP3 that cooperate to induce IL-1 and type I IFN for the regulation of Tfh responses." (PMID 33104760, 2020). "However, careful attention needs to be paid as to the potential propagation of bacterial infections by TLR3-induced production of type I IFNs." (PMID 33679711, 2020). "TLR3 has been well elucidated to be involved in both, the production of proinflammatory cytokines and the induction of type I IFNs, with the latter particularly occurring after viral or bacterial infections." (PMID 33519804, 2020). "In our study, TLR3 expression was also upregulated 22.5-fold postinfection, suggesting that this receptor might be involved in the immune response to bacterial infection in fish in addition to recognizing double-stranded RNA as in mammals." (PMID 20858287, 2010). "However, the precise mechanisms by which TLR3 mediates immunoregulation during bacterial infections remain unclear and require further investigation, particularly in the context of mammary gland immunity." (PMID 41305370, 2025). "However, the role of TLR3 in bacterial infections is poorly understood and remains controversial." (PMID 32824595, 2020).
bacterial infection (continued). "Further research on the TLR3 signaling could offer interesting possibilities for AD drug-development programs, since TLR3 is considered an essential component of various defensive responses against viral and bacterial infections and its activation induces inflammatory damage to the CNS." (PMID 37361208, 2023). "Placental TLR3 and TLR4 have been previously reported to induce premature termination of pregnancy upon detection of viral and bacterial infection, respectively." (PMID 34395439, 2021). "Thus, the increase of the combined response to TLR3 and TLR4 suggests that there may be a specific effect of combined viral and bacterial infection on peripheral dysfunction of the lung during allergic conditions." (PMID 26494305, 2015). "Given that TLR3 and TLR7 are antiviral receptors (Iqbal, Philbin & Smith, 2005) that are induced in response to viral challenge, it is not surprising that bacterial infection did not enhance their expression." (PMID 30701142, 2019). "Bacterial infection may also account for the previously reported constitutive high expression of TLR1, TLR2, TLR4, and TLR9 but not TLR3 in SGECs from SS patients." (PMID 32208441, 2020).
infectious disease (20 papers, 2013 to 2025). A disorder directly resulting from the presence and activity of a microbial, viral, or parasitic agent in humans. "Additionally, the disease/function networks that associated with AGE downregulated Casp1, Tlr3, Serp1, Irf1, Irf5, and Irf7 genes were involved in the antimicrobial response, inflammatory response, and infectious diseases." (PMID 27734935, 2016). "Across the broader immunopathologic landscape of infectious diseases, TLR3 is cemented as a critical immune modulator and is essential to understanding the multifaceted nature of host defense." (PMID 39988665, 2025). "L-pampoTM is our innovative adjuvant system containing TLR2 and TLR3 agonists, and it provides robust humoral and cellular immune responses against infectious diseases." (PMID 37568794, 2023). "L-pampoTM, a proprietary vaccine adjuvant of TLR2 and TLR3 agonists, promotes strong humoral and cellular immune responses against infectious diseases." (PMID 37568794, 2023). "Fourth, because TLRs are expressed in both non-neuronal and neuronal cell types in the CNS and contribute to both infectious and non-infectious disorders, TLR3 and TLR7 are thought to be major mediators of virus-induced signaling pathways during RSV infection." (PMID 29427996, 2018). "While TLR3 induction by dsRNA is a hallmark of anti-viral defense, TLR3 has also been shown to mediate inflammation in non-viral infectious diseases." (PMID 39988665, 2025). "Furthermore, EBER1 was detected in the sera of patients with active EBV-infectious diseases, suggesting that EBER1-meidated TLR3 signaling activation could account for the pathogenesis of active EBV-infectious diseases." (PMID 25101570, 2014). "Of note, although IRF1 signals are essential for infectious diseases and for the inflammatory response of TLR4, IRF1, NF-κB2 and STAT2 were predicted to exhibit higher activation under TLR3 stimulation." (PMID 26159724, 2015). "In summary, EBERs contribute to EBV infection-related pathogenesis, including cancer and active infectious diseases, through interactions with RIG-I and TLR3." (PMID 25101570, 2014). "Thus, the cross talk between TLR3 and IL-17A signaling via TICAM-1 is expected to be important to understand the pathogenesis of those serious infectious diseases, including recent coronavirus disease 2019." (PMID 34819358, 2022). "Since HSE patients were relatively resistant to infectious diseases outside the CNS, the TLR3/IFN pathway was proposed to be essential and non-redundant for CNS immunity against HSV-1." (PMID 31869396, 2019).
inflammation (11 papers, 2010 to 2025). Aberrant reaction of the microcirculation characterized by movement of fluid and leukocytes from the blood into extravascular tissues. "Additionally, innate immune activation via Toll‐like receptors (e.g., TLR3 sensing viral RNA) has been linked to the apoptosis of glandular cells and chronic inflammation in SS." (PMID 41294018, 2025). "MEX3B has been found to function as a coreceptor of TLR3 and promote TLR3 ligand-induced thymic stromal lymphopoietin production in nasal epithelial cells, thus contributing to the development of type 2 and eosinophilic inflammation in CRS." (PMID 36976645, 2023). "We found that TLR3-/- and MDA5-/- have distinct roles in the acute response to inhaled polyI:C, promoting epithelial barrier disruption and neutrophilic airway inflammation, respectively." (PMID 31067281, 2019). "Hence, the putative detrimental effect of reduced TLR3 expression by AMø of smokers on antiviral defenses might be partially offset by reduced responsiveness to necrosis-induced lung inflammation, an intriguing possibility that will require considerably greater investigation." (PMID 23497334, 2013). "In vivo studies using mice demonstrated that nasally administered poly(I:C) results in TLR3- and CXCR2-dependent neutrophilic pulmonary inflammation, bronchiolar epithelial hypertrophy, interstitial edema and altered lung function." (PMID 23947615, 2013). "Poly(I:C) is a synthetic ligand for TLR3, the only MyD88-independent TLR, allowing isolation of the effect of MyD88 deletion on ventilator-augmentation of lung inflammation." (PMID 21092115, 2010). "In RA, hyperactivated macrophages increased the expression of toll-like receptors (TLRs), such as TLR2, TLR3, TLR4, and TLR7, which induce synovial inflammation and cartilage destruction by releasing chemokines, pro-inflammatory cytokines, and degradative enzymes have been recognized." (PMID 36172378, 2022). "In conclusion, we found that TLR3 is a key regulator of epithelial barrier integrity in the lung, but it is not required for polyI:C-induced acute airway inflammation." (PMID 31067281, 2019).
neurological disorders (6 papers, 2014 to 2025). "Further experiments better powered to confirm our speculations are needed to then study the role of these potential sex differences in the sex dimorphism seen in many of neurological disorders linked to TLR3 activation early in life." (PMID 30971945, 2019). "Recently, Ghaemi and colleagues reported increased expression of TLR3 in ex vivo brain slices after CSD induction, indicating that TLR3 is a critical signaling molecule for CSD‐related neurological disorders." (PMID 40406905, 2025). "The role of the late pro-inflammatory response documented in female mice after TLR3 activation in the development of neurological disorders is unclear." (PMID 30971945, 2019). "Targeting TLR3 may be a novel strategy for developing new treatments for CSD-related neurological disorders." (PMID 35987639, 2022). "This apparent paradox could be explained by the hypothesis that TLR3 expression indeed facilitates the onset of the neurologic disease by supporting the TBEV penetration through BBB, but has a protective effect during the established CNS infection." (PMID 28646884, 2017). "Likewise, TLR3−/− mice infected with JEV showed more rapid signs of neurological disorder starting from 3 days pi, whereas TLR4−/− mice showed delayed signs of neurological disorder with a lower frequency of occurrence, compared to wild-type mice." (PMID 25188232, 2014). "Also, TLR3−/− (H-2b) mice showed faster neurological disorder and severely reduced body weight by JEV infection." (PMID 25188232, 2014). "Therefore, we aimed to determine whether each TLR signal pathway modulated neurological disease caused by JEV infection, using several TLR-deficient mice (TLR2, TLR3, TLR4, TLR7, TLR9)." (PMID 25188232, 2014).
cardiovascular disease (5 papers, 2022 to 2025). "Increasing evidence indicates that TLR3 plays a crucial role in the initiation and progression of cardiovascular diseases (CVDs)." (PMID 39828779, 2025). "Mouse studies have demonstrated the role of TLR3 in cardiovascular disease and tissue repair." (PMID 39828779, 2025). "Consequently, TLR3 represents a potential therapeutic target for modulating immune responses in cardiovascular diseases." (PMID 39828779, 2025). "TLR2, TLR3, and TLR4 are the TLRs that are predominately expressed in cardiomyocytes and play a large role in mediating inflammatory responses that are associated with cardiovascular disease." (PMID 37034342, 2023).
adenocarcinoma (4 papers, 2015 to 2023). A common cancer characterized by the presence of malignant glandular cells. "A light correlation between TLR3 and caspase-3 mRNA expression was observed in adenocarcinoma patients (all cases, Spearman coefficient 0.5682; only stage I, Spearman coefficient 0.6415)." (PMID 32093313, 2020). "Moreover, a correlation between TLR3 and caspase-3 mRNA expression in adenocarcinoma patients was investigated through the multiple gene analysis options of the KM-Plotter public NSCLC gene expression dataset." (PMID 32093313, 2020).
metabolic disorders (4 papers, 2019 to 2022). "In this study, the molecular characteristics and gene expression of chLECT2 were analyzed under the stimulation of toll-like receptor 3 (TLR3) ligand to understand the involvement of chLECT2 expression in chicken metabolic disorders." (PMID 31480179, 2019). "Therefore, there appears to be some potential dynamic between IL-33 and the TLR system, specifically TLR3 and TLR9, during the development of metabolic disease, which may be impacted by glucose-lowering medications." (PMID 31073344, 2019).
neurodegenerative disease (4 papers, 2010 to 2023). A disorder of the central nervous system characterized by gradual and progressive loss of neural tissue and neurologic function. "Finally, considering that activation of PRRs, such as TLR3, might be associated with pain and psychiatric and neurodegenerative diseases, it could be speculated that COX-2, mPGES-1, and PGE2 induced by this stimulus could partially contribute to the development of neuropathological conditions." (PMID 26780827, 2016).
respiratory diseases (4 papers, 2009 to 2024). "A better understanding of the effects of TLR3 activation will provide additional insight into the mechanisms underlying virus-induced exacerbations associated with respiratory diseases." (PMID 19486528, 2009). "A better understanding of the effects of TLR3 activation may provide insight into the mechanisms underlying virally-induced respiratory disease exacerbations." (PMID 19486528, 2009). "In summary, the data presented in this study suggest that sustained TLR3 activation may play an important role in respiratory disease pathogenesis." (PMID 19486528, 2009).
colorectal (3 papers, 2021 to 2024). "A murine model of Toll-like receptor 3 (TLR3)-mediated upper respiratory tract inflammation was used to investigate the impact of URIs on the olfactory system." (PMID 35012562, 2022).